MTMR12 (myotubularin related protein 12)
Description:
Acts as an adapter for the myotubularin-related phosphatases. Regulates phosphatase MTM1 protein stability and possibly its intracellular location. By stabilizing MTM1 protein levels, required for skeletal muscle maintenance but not for myogenesis (By similarity).
Synonyms: 3-PAP; KIAA1682; PIP3AP; FLJ20476; 3PAP
Tractability: PROTAC: ubiquitination databases record sites on it; its protein half-life has been measured.
Gene: Protein-coding gene on chromosome 5 (32,226,994 to 32,313,013, reverse strand). Ensembl gene ENSG00000150712.
Subcellular location: Cytoplasm; Sarcoplasmic reticulum; Cytoplasm, myofibril, sarcomere
Pathways (Reactome):
Metabolism: Synthesis of PIPs at the early endosome membrane
Gene Ontology:
Molecular function: protein binding; phosphatase activator activity
Biological process: phosphatidylinositol biosynthetic process
Cellular component: cytoplasm; cytosol; membrane; sarcoplasmic reticulum; sarcomere
Genetic constraint (gnomAD): Loss-of-function variants: 23 observed, 82.67 expected, observed/expected ratio (o/e) 0.28, 90% interval 0.2 to 0.39. The upper end of that interval is the gene's LOEUF score, 0.39, which puts it in group 1 of 6, group 1 being the genes least tolerant of losing a copy. Missense variants: 655 observed, 840.4 expected, observed/expected ratio (o/e) 0.78, 90% interval 0.73 to 0.83. Synonymous variants: 282 observed, 316.59 expected, observed/expected ratio (o/e) 0.89, 90% interval 0.81 to 0.98.
Homologues: Orthologues: chimpanzee MTMR12 (100% identical), macaque MTMR12 (99% identical), dog MTMR12 (94% identical), guinea pig MTMR12 (94% identical), rabbit MTMR12 (93% identical), pig MTMR12 (90% identical), mouse Mtmr12 (90% identical), rat Mtmr12 (89% identical), tropical clawed frog mtmr12 (64% identical), zebrafish mtmr12 (52% identical), Drosophila melanogaster CG14411 (29% identical), Caenorhabditis elegans mtm-10 (19% identical), and 10 more. Paralogues in human: MTMR10 (36% identical), MTMR11 (25% identical), SBF1 (20% identical), SBF2 (19% identical), MTMR1 (19% identical), MTMR2 (19% identical), MTMR3 (18% identical), MTMR4 (18% identical), MTMR9 (18% identical), MTM1 (17% identical), MTMR8 (16% identical), MTMR7 (16% identical), and 1 more.
Diseases named in the same sentence as MTMR12 in open-access papers:
MTMR12 is named in the same sentence as 10 diseases in open-access papers, as found by Europe PMC text mining. Sharing a sentence is not in itself a finding about the gene and the disease. The quoted sentences say what the papers report.
X-linked myotubular myopathy (2 papers, 2013 to 2024). A rare X-linked congenital myopathy characterized by numerous centrally placed nuclei on muscle biopsy and that presents at birth with marked weakness, hypotonia and respiratory failure. "The interaction between MTM1 and MTMR12 is essential for the stability of functional protein complexes in skeletal muscle, which offers novel targets for Mtm1 mutation-induced X-linked myotubular myopathy (XLMTM)." (PMID 38529329, 2024).
asthma (1 paper, 2013). "Of the top two regions, KCNIP4 and PDZD2/GOLPH3/MTMR12/ZFR, only KCNIP4 had gene-level replication in the SHARP AHR GWAS at a nominally significant level in the same regions as the asthma GWAS studies." (PMID 23457522, 2013).
Charcot-Marie-Tooth (CMT) disease (1 paper, 2013). "Mutations in genes encoding MTMR2 and MTMR13 have both been associated with Charcot-Marie-Tooth (CMT) disease raising the possibility that MTMR12 deficiency may result in neurological defects such as those seen in CMT." (PMID 23818870, 2013).
depression (1 paper, 2015). "Top association signals (P<1.0E−06) for %change in depression score include SNPs in the MTMR12 (myotubularin-related protein 12) gene." (PMID 25897834, 2015).
myopathies (1 paper, 2013). "Our studies revealed that deficiency of MTMR12 in zebrafish results in myopathy and impaired motor function similar to that caused by loss of myotubularin." (PMID 23818870, 2013). "As loss of MTMR12 results in reduction of myotubularin, we suspect that primary mutations of MTMR12 may result in centronuclear or related myopathies." (PMID 23818870, 2013).
MTMR12 also shares sentences with these, for which no sentence is quoted: Myotubular myopathy (2 papers); centronuclear myopathy (1); Insulin resistance (1); neuromuscular disease (1); Obesity (1).